NOTCH3 (notch receptor 3)
Diseases named in the same sentence as NOTCH3 in open-access papers (continued):
Sharing a sentence is not in itself a finding about the gene and the disease.
cholangiocarcinoma (6 papers, 2019 to 2024). A carcinoma that arises from the intrahepatic biliary tree (intrahepatic cholangiocarcinoma) or from the junction, or adjacent to the junction, of the right and left hepatic ducts (hilar cholangiocarcinoma). "In cholangiocarcinoma (CCA), more commonly known as bile duct cancer, Hhex was also found to be highly expressed and to operate in a positive feedback loop with Notch3, which itself is important in CCA, as well as inducing Wnt signalling." (PMID 37398663, 2023). "Genetic deletion of Notch3 in a mouse model of cholangiocarcinoma reduced tumour size and frequency, suggesting that NOTCH signalling, through NOTCH3 at least, is required for tumour initiation." (PMID 37605966, 2023). "A previous study using a mouse model of HCC and cholangiocellular carcinoma (CCC) induced by the overexpression of v-Akt and N-Ras oncogenes in hepatocytes reported the different effects of the blockade of Notch1, Notch2, and Notch3 signaling on the tumor progression." (PMID 35064244, 2022).
colorectal tumors (6 papers, 2013 to 2023). "For example, NOTCH3 overexpression is associated with poorly differentiated colorectal tumors, increased tumor growth rate, higher rates of venous invasion, and shorter recurrence-free survival." (PMID 37318881, 2023). "In the present work, we have shown that the expressions of Notch receptors were positively correlated with the in infiltration of macrophage, among which only Notch3 was highly expressed in colorectal tumor tissues and associated with poor prognosis of patients with CRC." (PMID 36647017, 2023). "LIN28B/CLDN1/NOTCH3 axis positively correlates with metastatic progression of human colorectal tumors." (PMID 37318881, 2023). "Meanwhile, miR-1 is also known to down-regulate Notch3 by directly-binding to its 3′UTR region in colorectal tumor cells." (PMID 35090386, 2022). "Our data indicate that aberrant Notch3 overexpression was observed in high proportion of colorectal tumors seen in 73% cases, and its expression was drastically associated with poor survival (p=0.0101)." (PMID 32211044, 2020). "Among the receptors, aberrant Notch3 and Notch4 overexpressions were observed in high percentage of colorectal tumors seen in 44/66 (73%) and 37/66 (56%) cases, respectively." (PMID 32211044, 2020). "Furukawa S and his colleagues demonstrates that miR-1 is downregulated in colorectal tumors and that miR-1 has the potential to suppress NOTCH3 expression through direct binding to its 3'-UTR region." (PMID 25803870, 2015). "Consistent with previous reports, we found that miR-1 is down-regulated in colorectal tumors and that miR-1 has the potential to suppress NOTCH3 expression by binding directly to its 3’-UTR region, which in turn results in a reduction in Asef gene expression." (PMID 24244701, 2013). "Here we show that NOTCH3 up-regulates Asef expression by activating the Asef promoter in colorectal tumor cells." (PMID 24244701, 2013). "In the present study, we showed that NOTCH3 signaling induces the expression of Asef in colorectal tumor cells." (PMID 24244701, 2013). "We found that endothelial DLL4 has the potential to induce colorectal tumor cell migration via NOTCH3 and Asef." (PMID 24244701, 2013). "Moreover, we demonstrate that microRNA-1 (miR-1) is down-regulated in colorectal tumors and that miR-1 has the potential to suppress NOTCH3 expression through direct binding to its 3’-UTR region." (PMID 24244701, 2013). "Furthermore, we demonstrate that microRNA-1 (miR-1) is down-regulated in colorectal tumor cells and that miR-1 has the potential to suppress NOTCH3 expression." (PMID 24244701, 2013). "qRT-PCR analysis revealed that NOTCH3, but not NOTCH1 or 2 mRNA levels are up-regulated in human colorectal tumor tissues compared to adjacent normal tissues." (PMID 24244701, 2013).
depression (6 papers, 2007 to 2025). "Among these, NOTCH3 was identified as a key player in depression-induced GC growth, associated with poor prognosis and immune cell infiltration." (PMID 40940884, 2025). "To elucidate the mechanisms underlying NOTCH3 activation in depression-associated GC progression, we performed comparative transcriptomics between TCGA-STAD database and CUS-treated PDX cohorts, identifying that 213 overlapping DEGs were identified." (PMID 40940884, 2025). "Depression was shown to decrease endogenous estradiol levels, resulting in the upregulation of NOTCH3, which facilitated GC progression by decreasing mitochondrial injury and shaping an immunosuppressive microenvironment." (PMID 40940884, 2025). "Depression-induced estrogen reduction leads to the activation of NOTCH3, which promotes GC growth through shaping an immunosuppressive microenvironment and reducing mitochondrial injury." (PMID 40940884, 2025). "Together, these data demonstrate that NOTCH3 depletion inhibits GC cell proliferation and reverses key features of tumor immunosuppression in the context of depression." (PMID 40940884, 2025). "In our study, NOTCH3 was identified as a key factor in depression-induced GC progression by regulating SOD2 activity and influencing cellular oxidative stress levels." (PMID 40940884, 2025). "Mechanistically, depression-induced estradiol reduction led to NOTCH3 upregulation, which prompted GC growth and altered immune cell composition, while exogenous estradiol supplementation alleviated this progression." (PMID 40940884, 2025). "Our work offers valuable insights into the role of E2 and NOTCH3 in depression-induced GC development; however, several limitations must be acknowledged." (PMID 40940884, 2025). "To further identify key DRGs in GC progression, we compared the top 20 depression related genes in cancer with our sequencing data from the PDXs, and NOTCH3 was the only overlapping gene." (PMID 40940884, 2025). "Further investigations are needed in preclinical models to clarify whether a particular threshold of NOTCH3 protein accumulation promotes cortical spreading depression." (PMID 40169951, 2025). "In terms of non-motor features, it seemed that depression, autonomic symptom dysfunction and fatigue were more frequently observed in NOTCH3-variant carriers." (PMID 36570541, 2022). "Positive MRI findings in asymptomatic individuals or in-patients who presented with depression or a psychiatric problem (Family B) indicated that NOTCH3 gene signalling may start early and may have different clinical presentations." (PMID 17996090, 2007). "To better understand the activities of NOTCH3 in GC with depression, we modified the NOTCH3 expression in the murine GC cell line YTN3 and the knockdown efficiency of NOTCH3 was successfully validated." (PMID 40940884, 2025).
intracerebral hemorrhage (6 papers, 2020 to 2025). A cerebrovascular disorder characterized by bleeding into one or both cerebral hemispheres including the basal ganglia and the cerebral cortex. "Notch3 mutant mice have been characterised and shown to be similar to human CADASIL, while mutations in Col4a1 genes result in intracerebral haemorrhages in mice and humans, and patients with Col4a1 mutations display white matter defects." (PMID 39543785, 2024). "Across subtypes, the highest hit rate (HR) was intracerebral hemorrhage (ICH, 7/18 = 38.9%), particularly with the etiological subtype of structural vasculopathy (4/4 = 100%, PVs in ENG, KRIT1, PKD1, RNF213); followed by ischemic small vessel disease (SVD, 15/48 = 31.3%; PVs in NOTCH3, HTRA1, HBB)." (PMID 36580209, 2023).
Marfan syndrome (6 papers, 2019 to 2025). A disorder of the connective tissue. "Therefore, future studies using strategies to specifically block NOTCH3 signalling in the mgR mouse model are required to strengthen and confirm the pathogenic role of NOTCH3 activation in driving emphysema development in Marfan syndrome." (PMID 36052538, 2022). "Considering the role of PDE5 in regulating the level of cGMP in smooth muscle cells, in this pilot study we sought to analyse PDE5, NOTCH1 and NOTCH3 expression in TAA patients with Marfan’s Syndrome, BAV and TAV." (PMID 31434939, 2019). "We found that NOTCH3 expression was increased in Marfan syndrome and TAV samples while NOTCH1 was up-regulated only in Marfan syndrome aortas, suggesting that the defects of extracellular matrix structure present in this syndrome can affect NOTCH expression." (PMID 31434939, 2019). "Although, there is no report showing the direct role of NOTCH3 signalling in COPD-associated emphysema, a recent study described that enhanced NOTCH3 signalling contributes to Marfan syndrome-associated pulmonary emphysema in mice (Ref." (PMID 36052538, 2022). "Marfan syndrome aortic root SMCs demonstrated a significant reduction in Notch3 expression with ERK blockade, whereas Notch1 and 2 did not significantly change." (PMID 31886938, 2020).
myocardial ischemia (6 papers, 2012 to 2025). A disorder of cardiac function caused by insufficient blood flow to the muscle tissue of the heart. "A study showed that the mechanism of OSM on cardiac ischemia/reperfusion injury is partially mediated by the NOTCH3/Akt pathway." (PMID 41018180, 2025). "Further in accordance with our data, another study illustrated that miR-1 targeted Notch3 in H9c2 cells under oxidative stress, resulting in aggravation of hypoxia-induced myocardial ischemia injury." (PMID 35090386, 2022). "Systemic delivery of Ad-Ang-1 resulted in a significant increase in Jagged 1 and Notch3 expression 24 hours after myocardial ischemia compared to Ad-β-gal." (PMID 22558265, 2012). "Thus, a novel role of NOTCH3/Akt signaling contributes to OSM-induced protection against cardiac ischemia/reperfusion injury." (PMID 41018180, 2025). "In addition, miR-1 can target the Notch3 gene to promote myocardial ischemia injury." (PMID 35090386, 2022). "On the contrary, promotion of the Notch3 production activated the downstream PI3K/Akt pathway and inhibited cardiomyocyte apoptosis, which alleviated cardiac ischemia/reperfusion injury." (PMID 34220548, 2021).
ovarian serous carcinoma (6 papers, 2010 to 2022). "The most highly expressed Notch3 ligand in ovarian serous carcinoma is Jagged 1, which is predominantly expressed in the mesothelial cells within the tumor microenvironment, suggesting a role for Notch3/Jagged 1 signaling in cell adhesion and proliferation." (PMID 30042330, 2018). "Our previous studies have demonstrated Notch3 gene amplification and upregulation in many ovarian serous carcinomas and Notch pathway activity contributed to drug resistance." (PMID 20953350, 2010). "We observed a significant correlation between Jagged1 expression and nuclear localization of the intracellular cytoplasmic domain of Notch3 (NICD3) in ovarian serous carcinoma tissues." (PMID 20953350, 2010). "By analyzing genome-wide DNA copy number changes in primary ovarian serous carcinoma, the most aggressive type of gynecologic cancer, we have identified a relatively frequent amplification located on chr19p13.12, which harbors Notch3." (PMID 20953350, 2010). "Moreover, recent large-scale genomic and epigenomic analyses of high-grade serous ovarian carcinomas by The Cancer Genome Atlas (TCGA) Network revealed altered Notch signaling in 22% of cases with alterations in Notch3 occurring in 50% of those cases." (PMID 25366565, 2014). "Although c-Kit has been reported to collaborate with Notch signaling in regulating multiple cellular functions, it is unclear whether c-Kit can regulate or activate Notch3, which plays an important role in CSC and high-grade ovarian serous carcinoma." (PMID 32169072, 2020). "The presence of a positive regulatory loop helps explain why Jagged1 is co-upregulated with Notch3 in ovarian serous carcinoma tissues in which gene amplification is detected in the Notch3 locus but not in the Jagged1 locus." (PMID 20953350, 2010).
pancreatic adenocarcinoma (6 papers, 2012 to 2025). "Several GEO databases of pancreatic adenocarcinoma revealed a positive correlation of ELF3 with Notch-3 and -4 transcripts." (PMID 37308977, 2023). "Tarextumab has recently tested in a phase II clinical trial for the treatment of pancreatic adenocarcinoma and pulmonary small cell carcinoma, which exhibit dysregulated NOTCH2 and/or NOTCH3 activity in tumor cells." (PMID 27124156, 2016). "Notch3 and HEY-1 have been shown to be prognostic biomarkers in pancreatic adenocarcinoma." (PMID 26673007, 2016).
Parkinson disease (6 papers, 2021 to 2024). A progressive degenerative disorder of the central nervous system characterized by loss of dopamine producing neurons in the substantia nigra and the presence of Lewy bodies in the substantia nigra and locus coeruleus. "One patient with NOTCH3 mutations presented with typical parkinsonism and had a poor response to levodopa treatment." (PMID 37237429, 2023). "Previous studies have established a link between NOTCH3 variants and Parkinson’s disease (PD) in terms of neuropathology and clinical characteristics." (PMID 36570541, 2022). "Features of parkinsonism were found in 6/17 (35.3%) of patients with pathogenic NOTCH3 mutations, 3/17 (17.6%) of which presented with parkinsonism as the initial complaint." (PMID 33597917, 2021). "We found that 6/17 (35.3%) of NOTCH3 positive patients in our cohort had features of parkinsonism, while 3/17 (17.6%) presented with parkinsonism as the first symptom." (PMID 33597917, 2021). "NOTCH3 may impact small vessel diseases, while GBA is known to play a role in Parkinson’s disease." (PMID 39273625, 2024).
Sepsis (6 papers, 2016 to 2023). Sepsis is defined as life-threatening organ dysfunction caused by a dysregulated host response to infection. "Overall, these findings suggested that omega-3 FAs modulated the miR-1-3p/Notch3/Smad axis, thereby reducing intestinal epithelial inflammation and oxidative stress injury caused by sepsis." (PMID 35090386, 2022). "Collectively, our findings indicated that omega-3 FAs elevate the expression of Notch3 by down-regulating miR-1-3p, and then blocking the Smad pathway to alleviate intestinal epithelial inflammation and oxidative stress injury caused by sepsis." (PMID 35090386, 2022). "Our discoveries provide a deeper and better understanding of the protective mechanism of the miR-1-3p/Notch3/Smad axis in sepsis-induced intestinal injury." (PMID 35090386, 2022). "Altogether, these data and evidences are highly-suggestive of the critical role of Smad pathway inhibition Notch3 in sepsis-induced intestinal injury." (PMID 35090386, 2022). "In conclusion, sepsis significantly attenuated the Notch (especially Notch3) signaling in mouse aorta along with reduction in contractile gene expression and vasoconstriction response." (PMID 35190630, 2022). "In summary, findings obtained in our study indicate that omega-3 FAs are capable of inactivating the miR-1-3p/Notch3/Smad axis, and consequently alleviating sepsis-induced intestinal injury." (PMID 35090386, 2022). "As such we are the first to illustrate that omega-3 FAs impair miR-1-3p-mediated inhibition of Notch3 to alleviate sepsis-induced intestinal injury." (PMID 35090386, 2022). "Among those genes, Notch3 was found to be significantly down-regulated in sepsis as evidenced by the GSE53007 dataset." (PMID 35090386, 2022). "Here, for the first time, we demonstrate that AA is a novel small molecule inhibitor of the Notch signaling pathway and exerted anti-sepsis effects by preventing Notch3 from binding to the IL-6 promoter and regulating mitochondrial function." (PMID 29599924, 2018). "Furthermore, in vivo experimentation in our study illustrated that omega-3 FAs impaired the miR-1-3p-mediated inhibition of Notch3 and disrupted the Smad pathway to attenuate sepsis-induced intestinal injury with the help of murine models." (PMID 35090386, 2022). "Accordingly, the current study set out to explore if omega-3 FAs could affect sepsis-induced intestinal injury with the involvement of the microRNA (miR)-1-3p/Notch3-Smad axis." (PMID 35090386, 2022). "However, sepsis-mediated down-regulation of Notch3 and its contribution to vascular hyporeactivity needs to be established in future using genetic approach." (PMID 35190630, 2022). "In the present study, we have also observed that when septic mice were treated with 1400 W at the same dose rate 57 there was significant restoration of aortic Notch3 mRNA expression suggesting a predominant role of iNOS-derived NO in sepsis-induced down-regulation of Notch3 in mouse aorta." (PMID 35190630, 2022). "Our previous study suggests that PHD2 may regulate lung microvascular pericyte/EC coverage via upregulation of HIF-2α and Notch3 signaling pathways in the LPS-induced sepsis model." (PMID 27613846, 2016). "Thus it may not be unreasonable to infer that the changes observed in the Notch targets following sepsis were attributed to the change in the activity of both Notch1 and Notch3 signalling." (PMID 35190630, 2022). "Furthermore, we explored whether Notch3 regulates sepsis-induced intestinal injury via inhibition of Smad signaling." (PMID 35090386, 2022). "In sepsis, LPS suppresses Sirt3 expression, which disrupts angiopoietins/Tie-2 and HIF-2α/Notch3 signaling pathways; thus leading to a reduction of pericyte/capillary coverage, subsequently promoting vascular leakage, inflammation and end-organ dysfunction." (PMID 26868537, 2016).
asthma (5 papers, 2014 to 2023). "Overall, these studies highlight the complexity of NOTCH signalling in asthma pathogenesis, where it is evident that different NOTCH receptors (including NOTCH3) regulate pathogenic or asthma-protective responses in a context-dependent manner." (PMID 36052538, 2022). "In the OVA‐induced asthma mice model, Notch1, Notch2 and Notch3 were all highly expressed in the lung tissues." (PMID 32935466, 2020). "Of note, Notch1, Notch2 and Notch3 are strongly overexpressed in the lung tissues of rats with ovalbumin‐induced asthma, and Notch1 inhibition by emodin treatment confers more remarkable transformations within the lung tissue than does Notch2 and Notch3 inhibition." (PMID 35355403, 2022).
esophageal squamous cell carcinoma (5 papers, 2019 to 2025). Esophageal squamous cell carcinoma (ESCC) is a type of esophageal carcinoma (EC) that can affect any part of the esophagus, but is usually located in the upper or middle third. "For instance, knockdown of NOTCH3 upregulated ZEB1 expression in esophageal squamous cell carcinoma." (PMID 31019894, 2019). "CircRNA‐mediated modulation of NOTCH 3 is also involved in the pathogenesis of esophageal squamous cell carcinoma (ESCC)." (PMID 40761890, 2025). "Notch3 may predict better clinical outcomes in esophageal squamous cell carcinoma patients." (PMID 34042293, 2021). "Interestingly, analysis of microarray data of NOTCH3 knockdown (GSE27424) showed that silencing NOTCH3 results in a significant increase of ZEB1 and a significant decrease of IRF6 in esophageal squamous cell carcinoma." (PMID 31019894, 2019).
glomerular diseases (5 papers, 2010 to 2025). "In agreement with this notion, previous studies in our lab showed that transfection of podocytes with Notch3 altered phenotype and induced cell proliferation contributing and accelerating the progression of glomerular disease." (PMID 35611804, 2022). "Notch3 activation is significantly increased in various glomerular diseases, renal tubulointerstitial diseases, glomerular sclerosis, and renal fibrosis and mediates disease occurrence and development." (PMID 33149805, 2020). "Because the Notch pathway is activated in glomerular diseases with or without HIV-1, it remains to be determined whether HIV-1 can induce the activation of Notch3 directly." (PMID 39910908, 2025).